CLUH (CLUH binding protein of NUMT mRNA)
Description:
mRNA-binding protein involved in proper cytoplasmic distribution of mitochondria. Specifically binds mRNAs of nuclear-encoded mitochondrial proteins in the cytoplasm and regulates transport or translation of these transcripts close to mitochondria, playing a role in mitochondrial biogenesis.
Synonyms: CLU1; formerly KIAA0664
Tractability: PROTAC: ubiquitination databases record sites on it; its protein half-life has been measured.
Gene: Protein-coding gene on chromosome 17 (2,689,386 to 2,712,663, reverse strand). Ensembl gene ENSG00000132361.
Subcellular location: Cytoplasm; Cytoplasmic granule
Subcellular location (Human Protein Atlas): Vesicles; Nucleoli fibrillar center
Gene Ontology:
Molecular function: mRNA binding; protein binding
Biological process: intracellular distribution of mitochondria; mitochondrion organization
Cellular component: cytoplasm; mitochondrion
Genetic constraint (gnomAD): Loss-of-function variants: 75 observed, 113.71 expected, observed/expected ratio (o/e) 0.66, 90% interval 0.55 to 0.8. The synonymous counts are far from expectation, so gnomAD's model fits this gene poorly and the ratio says little. Missense variants: 1,840 observed, 1,731.8 expected, observed/expected ratio (o/e) 1.06, 90% interval 1.02 to 1.1. Synonymous variants: 989 observed, 747.65 expected, observed/expected ratio (o/e) 1.32, 90% interval 1.25 to 1.39.
Homologues: Orthologues: chimpanzee CLUH (99% identical), macaque CLUH (97% identical), rabbit CLUH (96% identical), guinea pig CLUH (95% identical), mouse Cluh (95% identical), rat Cluh (95% identical), pig CLUH (94% identical), dog CLUH (94% identical), tropical clawed frog cluh (78% identical), zebrafish cluha (76% identical), Drosophila melanogaster clu (54% identical), zebrafish cluhb (45% identical), and 1 more.
Diseases named in the same sentence as CLUH in open-access papers:
CLUH is named in the same sentence as 13 diseases in open-access papers, as found by Europe PMC text mining. Sharing a sentence is not in itself a finding about the gene and the disease. The quoted sentences say what the papers report.
ulcerative colitis (2 papers, 2023 to 2025). An inflammatory bowel disease involving the mucosal surface of the large intestine and rectum. "Reduced CLUH gene expression increases ROS production, reduces mitophagy and lysosomal function in macrophages, and was reported in ulcerative colitis." (PMID 39992598, 2025).
Arthritis (1 paper, 2025). Inflammation of a joint. "In cases with EN and arthritis, pathogenic variants of CLUH and IL36RN genes were detected." (PMID 39992598, 2025).
cardiac hypertrophy (1 paper, 2025). "CLUH (pLI = 0.99), encodes an mRNA-binding protein involved in intracellular distribution and biogenesis of mitochondria, linked to cardiac hypertrophy." (PMID 40127276, 2025).
colitis (1 paper, 2023). Inflammation of the colon. "Remarkably, our studies in the mouse model of colitis with CLUH knockdown displayed exacerbated disease pathology." (PMID 37140992, 2023). "Interestingly, mitochondrial pathways were previously shown to be altered in the DSS-induced colitis model, and we used this model to understand in vivo function of CLUH." (PMID 37140992, 2023).
liver cancer (1 paper, 2024). An epithelial or non-epithelial malignant neoplasm that arises from the liver. "We identified YWHAE as significantly associated with liver fibrosis, AVIL, FIS1, MUC1, ACOT7, CLUH, HNF4A, and TNFSF10 with liver cancer, and AVIL with liver disease-related mortality (FDR-adjusted P values < 0.05)." (PMID 38862964, 2024).
cancer (1 paper, 2022). A tumor composed of atypical neoplastic, often pleomorphic cells that invade other tissues. "We propose that expression of astrin-2 endows cancer cells with the ability to proliferate, despite a dysregulated coupling between mitochondrial metabolism and the cell cycle, making CLUH a possible novel therapeutic target in cancers overexpressing SPAG5." (PMID 35559794, 2022). "HeLa cells, as many human cancer cells, overexpress not only astrin-1 but also astrin-2, an isoform of astrin competent to bind all other interactors (kinastrin, DYLNN1, and MYCPB) and the kinetochore, but not CLUH." (PMID 35559794, 2022).
infection (1 paper, 2019). The state of being infected such as from the introduction of a foreign agent such as serum, vaccine, antigenic substance or organism. "(A–E) A549 cells were pretreated (48 hr) with siRNA (50 nM) for clustered mitochondria homolog (CLUH), or scrambled siRNA control (scr) followed by infection with RSV (MOI 1) for another 24 hr." (PMID 31246170, 2019). "As observed previously, CLUH-targeting siRNA but not control scrambled siRNA induced mitochondrial perinuclear clustering in mock infected cells (first two rows), with RSV-infection resulting in only a further slight increase in clustering (4th row)." (PMID 31246170, 2019).
neurodegenerative disease (1 paper, 2024). A disorder of the central nervous system characterized by gradual and progressive loss of neural tissue and neurologic function. "It will be interesting to explore whether dysfunctional CLUH plays any role in the pathogenesis of these neurodegenerative diseases." (PMID 38809982, 2024).
peripheral neuropathy (1 paper, 2024). A disorder affecting the peripheral nervous system. "We show that CLUH, which binds mRNAs encoding mitochondrial proteins, prevents peripheral neuropathy and motor deficits in the mouse." (PMID 38809982, 2024). "Together, we identify CLUH as a crucial player for the expression of mitochondrial proteins in axons and show the physiological role of CLUH to prevent peripheral neuropathy." (PMID 38809982, 2024).
CLUH also shares sentences with these, for which no sentence is quoted: cervical cancer (1 paper); liver disease (1); liver fibrosis (1); ovarian carcinoma (1).